IDH2 (isocitrate dehydrogenase (NADP(+)) 2)
Diseases named in the same sentence as IDH2 in open-access papers (continued):
Sharing a sentence is not in itself a finding about the gene and the disease.
brain tumors (27 papers, 2011 to 2025). "Brain tumors harboring mutations in genes IDH1 or IDH2 can be identified by DESI-MS due to the accumulation of the oncometabolite 2-hydroxyglutarate (2-HG)." (PMID 39595159, 2024). "We describe a novel DNA methylation epi-signature that specifically distinguishes brain tumors having oncogenic IDH1/IDH2 variants from tumors with normal IDH1/IDH2." (PMID 36360312, 2022). "Some reports have demonstrated that mutations in IDH1 and IDH2 are recurrent in brain tumors." (PMID 29312565, 2017). "Utilizing live analysis of nanopore sequencing data, we evaluated the brain tumor-associated molecular markers IDH1 R132, IDH2 R172, pTERT C228 and C250, H3F3A K27 and G34, Hist1H3B K27, and BRAF V600." (PMID 39606159, 2024). "The two-3D stochastic microsensors proposed for the molecular recognition of IDH1 and IDH2 were reliably used for screening tests of biological samples such as brain tumor tissue samples and whole blood samples." (PMID 35159804, 2022). "The aim of this study is to investigate the prevalence of IDH1105GGT in a cohort of brain tumors, and its association with clinicopathologic features and IDH1 and IDH2 missense mutations." (PMID 29535392, 2018). "Exon 4 of IDH1 and IDH2 was analyzed in a series of brain tumors classified according to current WHO criteria." (PMID 29535392, 2018). "Taken together, identifying critical gene mutations in brain tumors is gaining clinical relevance as, for example IDH1 and IDH2 mutations bear predictive and prognostic preposition." (PMID 27454254, 2016). "In brain tumors, the best evidence that metabolic enzymes play a causative role comes from the discovery of the IDH1 and IDH2 mutations." (PMID 23229761, 2013). "Out of 135 brain tumor samples tested, 28 (20.7%) had one clinically relevant variant, 11 (8.1%) had a BRAF Val600Glu variant, 14 (10.3%) had an IDH1 Arg132 variant, and 3 (2.2%) had an IDH2 Arg172 variant." (PMID 37483495, 2023). "If IDH loss-of-function alone is critical for tumourigenesis, we might expect IDH3 mutations to occur in brain tumours, including those sub-types with relatively low frequencies of IDH1 and IDH2 mutations." (PMID 21625441, 2011). "Frequency and/or type of mutations in genes encoding isocitrate dehydrogenase 1 (IDH1), isocitrate dehydrogenase 2 (IDH2), and epidermal growth factor receptor (EGFR) vary between histological types of primary brain tumors." (PMID 27454254, 2016). "A total of 68 brain tumors were assessed for IDH1 and IDH2 promoter methylation status." (PMID 23267435, 2012).
lung carcinoma (27 papers, 2014 to 2025). "In batch 2, CEACAM5 and IDH2 demonstrated identical results in the brushings, and as expected, the low-risk group is significantly different from the lung cancer group." (PMID 37760474, 2023). "We found that high IDH2 expression was associated with poor survival in lung cancer patients undergoing chemotherapy." (PMID 36831011, 2023). "In the univariate analysis, compared to the low-risk group, AKR1B10, ALDH3A1, CEACAM5, and IDH2 are higher than the high-risk or cancer group, i.e., their upregulation discriminates the low-risk group from the high-risk group as well as the lung cancer group." (PMID 37760474, 2023). "In this study, we examined the association between IDH2 and survival among lung cancer patients undergoing cisplatin chemotherapy and radiotherapy." (PMID 36831011, 2023). "A germline variant (rs11540478) within the IDH2 gene is associated with an increased risk of lung cancers." (PMID 32333643, 2020). "Functional analysis showed higher IDH2 expression and increasing cell viability among T alleles; IDH2 mRNA was higher in peripheral blood lymphocytes from patients with lung cancer compared to healthy control subjects." (PMID 29465809, 2018). "In a previous study, we showed that a new IDH2 genetic variant rs11540478 is associated with a risk of lung cancer." (PMID 29465809, 2018). "Thus, we subcutaneously injected cancer cells (LLC1, lung carcinoma cells) into 8-week-old WT and IDH2-deficient mice." (PMID 39256649, 2024). "We also examined the effects of combining IDH2 inhibition with cisplatin or radiation for the treatment of lung cancer and explored the mechanisms underlying the combination effect, with a focus on the impact of IDH2 abrogation on mitochondrial metabolism and ROS generation." (PMID 36831011, 2023). "To determine whether ROS stress might be a potential mechanism for enhancing the cytotoxic effect of cisplatin caused by IDH2 inhibition, we first measured ROS levels in lung cancer cells treated with AGI-6780, cisplatin, or their combination." (PMID 36831011, 2023). "A recent study showed that functional IDH2 variant might be associated with increased risk of lung cancer development." (PMID 29769567, 2018). "In our previous study, we found that IDH2 polymorphism rs11540478 is a risk factor for lung cancer." (PMID 29465809, 2018). "In our previous study, we showed that idh2 rs11540478 is a risk factor for lung cancer." (PMID 29465809, 2018). "High expression of wild-type IDH2 was shown to contribute to the survival of lung cancer cells, esophageal squamous cell carcinoma, and hepatocellular carcinoma cells." (PMID 38658533, 2024). "Our recent study showed that wild-type IDH2 was highly expressed in lung cancer cells and promoted tumor growth." (PMID 38658533, 2024). "Our study has identified the mitochondrial metabolic enzyme IDH2 as an important redox regulator in lung cancer cells, in which it helps to maintain redox homeostasis." (PMID 36831011, 2023). "The higher levels of IDH2 mRNA expression were also consistently observed in the drug-resistant lung cancer cells and ovarian cancer cells in the GEO datasets." (PMID 36831011, 2023). "The ability of IDH2 to promote resistance to cisplatin seems to provide an explanation for the poorer clinical outcome in lung cancer patients with high IDH2 expression compared to those with low IDH2 expression among the patients in the chemotherapy group." (PMID 36831011, 2023). "Inhibition of IDH2 significantly enhanced the anticancer activity of cisplatin and also increased the effect of radiation against lung cancer cells." (PMID 36831011, 2023). "First, we analyzed the available data from the databases gene expression omnibus (GEO) database to evaluate the clinical relevance of IDH2 expression in affecting lung cancer patient survival." (PMID 36831011, 2023).
lung carcinoma (continued). "We show that IDH2 is elevated in cisplatin-resistant lung cancer cells and promotes tumor cell survival through a mitochondrial redox metabolism to enhance antioxidant capacity." (PMID 36831011, 2023). "We then generated a stable IDH2-knockdown lung cancer cell line using a lentivirus-based method for in vitro and in vivo study." (PMID 36831011, 2023). "Our study showed that a specific knockdown of wild-type IDH2 in lung cancer cells increased their sensitivity to cisplatin in a mouse xenograft model." (PMID 36831011, 2023). "Our study showed that inhibition of IDH2 indeed increased the sensitivity of lung cancer cells to radiation in colony formation assay." (PMID 36831011, 2023). "We then used AGI-6780, a pharmacological inhibitor of IDH2, to further test its effect on cellular sensitivity to cisplatin and radiation, which is also a major therapeutic modality in lung cancer treatment." (PMID 36831011, 2023). "Inhibition of IDH2 increases the sensitivity of lung cancer cells to cisplatin, and potentially radiation, through a ROS-mediated mechanism." (PMID 36831011, 2023). "Cell growth, apoptosis, cell viability, and colony formation assays were conducted to test the sensitivity of lung cancer cells with different IDH2 expression status to cisplatin or radiation treatment in vitro." (PMID 36831011, 2023). "This study aims to test the potential of targeting IDH2 as a therapeutic strategy to inhibit lung cancer in vitro and in vivo." (PMID 36831011, 2023). "Together, these data suggest that it would be feasible to use a pharmacological inhibitor of IDH2 to increase the sensitivity of lung cancer cells to conventional chemotherapy and radiotherapy." (PMID 36831011, 2023). "In a previous work, we found that IDH2 was upregulated in lung cancer and promoted lung cancer cell proliferation and tumor growth." (PMID 36831011, 2023). "To further test the role of IDH2 on cisplatin resistance, we generated a stable IDH2-knockdown lung cancer cell line using a lentivirus-mediated shRNA approach." (PMID 36831011, 2023). "Our previous study showed that high expression of wild-type IDH2 promotes the proliferation of lung cancer cells." (PMID 36831011, 2023). "In this study, we showed that IDH2 was upregulated in drug-resistant lung cancer cells and enhanced cancer cell survival in the presence of cisplatin treatment." (PMID 36831011, 2023). "Tumor tissues expressed lower levels of miR-101 than adjacent normal tissues and a higher amount of IDH2, which are in line with the literature that IDH2 was overexpressed in lung cancer." (PMID 36304962, 2022). "Studies demonstrated that IDH2/HIF1α pathway was responsible for cancer proliferation, such as cervical cancer and lung cancer." (PMID 36304962, 2022). "For Warburg effect, previously study also found that IDH2 promoted the Warburg effect and lung cancer cell growth, which is mediated through HIF1α activation followed by decreased α-KG." (PMID 34513821, 2021). "Three genes (TET1, ARID1B, and BAZ1A) are highly mutated in breast and lung cancer types, whereas TET1, IDH2, and ARID1B were also among the top genes altered in several cancer types, further corroborating their putative role as cancer drivers." (PMID 32963031, 2020). "Previous studies have reported upregulation of wild-type IDH2 in lung cancer, ovarian cancer, endometrioid carcinoma, and advanced colorectal cancer." (PMID 31599393, 2020). "IDH2 overexpression in lung cancer cell lines decreased αKG and ROS, and induced HIF1α and Warburg effect, resulting in cell growth increase." (PMID 31010244, 2019). "We found that IDH2 was higher in serum from patients with lung cancer compared to healthy control subjects." (PMID 29465809, 2018). "Here, we found that the IDH2 protein was elevated in a time‐ and cell number‐dependent manner in the culture medium in which lung cancer cells were grown." (PMID 29465809, 2018).
lung carcinoma (continued). "We found that the level of IDH2 in serum can differentiate lung cancer patients from healthy controls with an AUC of 0.83 (95% confidence interval = 0.79 to 0.88)." (PMID 29465809, 2018). "Of these, Aco2, Idh2, Ndufs1, Hadh, Dlat, Itgam, Dlat, Hadha, Mrpl11, Dlst, and Hspd1 show potential as oncoproteins and tumor suppressors and warrant further study for their possible role in inflammation-driven lung cancer." (PMID 40429836, 2025). "Previous studies discovered that the IDH2 protein was enhanced in lung cancer cells." (PMID 39113352, 2024). "In addition, IDH2 overexpression in lung cancer cells increased the reverse response of the TCA cycle; promoted anaerobic glycolysis, glutamine breakdown, and lactate production; and reduced cellular ATP content." (PMID 38577683, 2024). "Together, these data showed that IDH2 could be a prognostic factor for lung cancer patients who received chemotherapy and suggested the possibility that IDH2 might affect the drug sensitivity of lung cancer cells." (PMID 36831011, 2023). "IDH2 was upregulated in cisplatin-resistant lung cancer cells, which could be sensitized by targeted inhibition of IDH2." (PMID 36831011, 2023). "However, the mechanism by which IDH2 promotes lung cancer and its therapeutic potential have yet to be further investigated." (PMID 36831011, 2023). "Mechanistic study showed that abrogation of IDH2 caused only minimal changes in oxygen consumption rate (OCR) and extracellular acidification rate (ECAR) in lung cancer cells, but induced a significant increase in ROS, which rendered the cancer cells more sensitive to cisplatin." (PMID 36831011, 2023). "Our study suggests that mitochondrial wild-type IDH2 could be a potential new target to enhance the therapeutic effect of cisplatin and radiotherapy in lung cancer." (PMID 36831011, 2023). "Pretreatment of lung cancer cells with the ROS scavenger N-acetyl-cysteine could partially rescue cells from the cytotoxic effect of cisplatin and IDH2 inhibition." (PMID 36831011, 2023). "Our study showed that IDH2 might play an important role in cisplatin resistance, and that abrogation of IDH2 could increase the sensitivity of lung cancer cells to cisplatin." (PMID 36831011, 2023). "Considering that cisplatin is a front-line chemotherapeutic drug of choice for the treatment of lung cancer, we analyzed the potential relationship between IDH2 expression and cisplatin sensitivity in lung cancer cells using A549 cell line and its cisplatin-resistant sub-line, A549-CR." (PMID 36831011, 2023). "Importantly, abrogation of IDH2 significantly increased the sensitivity of lung cancer cells to cisplatin in vivo." (PMID 36831011, 2023). "The inhibitory effect was most potent in the xenografts harboring IDH2-shRNA and treated with cisplatin (blue curve), suggesting that targeting IDH2 could sensitize lung cancer cells to cisplatin in vivo." (PMID 36831011, 2023). "The primary diseases included germinomas (n = 2), acute lymphoblastic leukemias (n = 2), medulloblastomas (n = 3), diffuse astrocytoma with IDH2 mutant (n = 1), pilocytic astrocytoma (n = 1), pituitary adenoma (n = 1), and a metastatic brain tumor from lung cancer (n = 1)." (PMID 35505351, 2022). "Wild-type IDH2 overexpression is an indicator of poor outcome in lung cancer through the stimulation of the Warburg effect to help the maintenance of cancer cells via activation of hypoxia inducible factor 1α (HIF1α) which supports tumour growth in hypoxic environments." (PMID 31599393, 2020). "Furthermore, IDH2 expression was found to be higher in lung cancers as compared to normal lung tissues." (PMID 31010244, 2019). "Here, we found IDH2 protein was elevated in the culture supernatant fraction of lung cancer cells." (PMID 29465809, 2018). "Due to the function of IDH2 protein, IDH2 in the culture medium may promote proliferation and viability of lung cancer cells." (PMID 29465809, 2018).
lung carcinoma (continued). "Results indicated that the protein level of IDH2 in serum could differentiate the patient with lung cancer from the healthy control subject." (PMID 29465809, 2018). "The high expression of IDH2 in lung cancer cells and the location of IDH2 suggested that IDH2 might be secreted out of the cells." (PMID 29465809, 2018). "IDH2 can be used as an adjunctive biomarker for diagnosis in lung cancer." (PMID 29465809, 2018). "Interestingly, the IDH2 frequently showed overexpression rather than a mutation in the bladder, breast, and lung cancers." (PMID 35880695, 2023). "To evaluate the impact of IDH2 on lung cancer growth in vivo and the therapeutic activity of cisplatin in mice, we performed an animal study using tumor xenografts with A549 cells containing wild-type IDH2 or IDH2 knockdown (stable) via shRNA mediated by a lentiviral vector." (PMID 36831011, 2023). "Downregulating IDH2 leads to increased α-KG and consequently decreased HIF-1α expression, reducing lung cancer cell proliferation and promoting cellular glucose uptake and lactate production." (PMID 36497259, 2022). "Most studies indicate that IDH2 is also significantly upregulated in ESCC,132 ovarian cancer, lung cancer and other types of cancer, playing a pro-oncogenic role." (PMID 33028807, 2020). "In this study, we first analyzed the protein expression of IDH2 in cell culture medium in which two lung cancer cell lines, NCI‐H460 and A549, were growing and found that the IDH2 level is increased in a time‐ and cell number‐dependent manner." (PMID 29465809, 2018). "We found that the expression levels of IDH2 were negatively correlated with overall survival (OS) in lung cancer patients treated with chemotherapy (p = 0.009), but not in lung cancer patients who did not undergo chemotherapy, suggesting that IDH2 could potentially affect drug sensitivity." (PMID 36831011, 2023). "In total, 57.1% of these patients had no therapy option, since PIK3CA (14.3%), IDH2 (7.1%), and MTOR (7.1%) are not actionable lung cancer genes." (PMID 39769478, 2024).
myeloid malignancies (21 papers, 2013 to 2025). "By contrast, mutations in genes such as SRSF2 and IDH2 afforded similar HRs for different types of myeloid neoplasms." (PMID 37620601, 2023). "(iii) IDH1 and IDH2 mutations are also rarely present in preleukemic myeloid malignancies: 0.8–4% in chronic phase MPN, 4–14% in MDS, but its frequency increases up to 20–25% in blast phase transformation." (PMID 34153064, 2021). "Indeed, at least one pathogenic mutation (WT1, FLT3-ITD, IDH2 or PTPN11 mutation) has been identified in all the reported myeloid tumors harboring NPM1::MLF1." (PMID 39443736, 2024). "Enasidenib, an IDH2 inhibitor, was the first to be approved on the basis of a phase Ib/II trial that assessed safety, and clinical activity in patients with IDH2-mutated advanced myeloid malignancies." (PMID 32256698, 2020). "In support of this possibility, mutations of IDH1 and IDH2 also occur in myeloid malignancies where neomorphic activity of the enzyme results in aberrant generation of 2-hydroxyglutarate, which inhibits the 2-oxoglutarate dependent conversion of 5mC to 5hmC by TET2." (PMID 25276435, 2014). "In the absence of these three major driver mutations, screening for other mutations associated with myeloid neoplasms, such as ASXL1, EZH2, TET2, IDH1, IDH2, SRSF2, and SF3B1, can help establish the clonal nature of the disease." (PMID 41514563, 2025). "ASXL1mt in myeloid neoplasms were considered to be ubiquitously accompanied by mutations of RUNX1, SRSF2, STAG2, NRAS, or IDH2, in addition to wild‐type NPM1 and FLT3,14, 21, 22, 28 which was aligned with the mutation profile in our cohort." (PMID 38146893, 2023). "Each SF is also associated with a distinct pattern of mutations in other genes commonly detected in myeloid malignancies, as in the case of SRSF2 mutations with TET2 mutations in CMML and with RUNX1, IDH2, and ASXL1 mutations in AML." (PMID 31766606, 2019). "Interestingly, glial and myeloid malignancies are both also frequently mutated in IDH1 and IDH2." (PMID 38066546, 2023). "Interestingly, no IDH1 mutations have been mapped in AITL as yet, and only the IDH2 R172 mutant but not IDH2 R140 (a frequent mutation in myeloid neoplasms) has been documented." (PMID 29148847, 2018).